PIK3CA (phosphatidylinositol-4,5-bisphosphate 3-kinase catalytic subunit alpha)
Diseases named in the same sentence as PIK3CA in open-access papers (continued):
Sharing a sentence is not in itself a finding about the gene and the disease.
tumor (continued). "At present only class I PI3Ks have been shown to be associated with cancer: indeed PIK3CA, the gene which encodes for p110α PI3K, is mutated in a variety of tumor types." (PMID 27494886, 2016). "In the multivariate analysis, we selected sex, age, tumor differentiation, nodal stage, KRAS, BRAF and PIK3CA gene mutations in relation to DFS and OS by stage and in both stages combined together." (PMID 27074743, 2016). "AOA treatment consistently reduced amounts of α-KG and alanine, but increased amounts of glutamate and pyruvate, in the HCT116 PIK3CA mutant tumours." (PMID 27321283, 2016). "A total of 157 patients with diverse advanced cancers with known FFPE tumor tissue mutation status for mutations in at least one of the selected cancer genes, which included BRAF, EGFR, KRAS, PIK3CA, were enrolled." (PMID 25980577, 2015). "Two human tumor xenograft models with known KRAS and PIK3CA mutations (CUCRC40 and CUCRC98) were treated with alisertib and trametinib as single agents and in combination at various doses: alisertib 10 and 20 mg/kg and trametinib 0.5 and 1.5 mg/kg." (PMID 26136684, 2015). "However, mutation analysis from a single patient has identified an activating mutation in PIK3CA from the primary tumor, and RNA-seq datasets demonstrated overexpression of AKT2 mRNA in one of two areas of recurrence, perhaps suggesting that this pathway may be an important area for future research." (PMID 26793165, 2015). "Analysis of PIK3R1, PIK3R3 and PIK3CA mRNA expression in these datasets revealed that PIK3R1 was significantly down-regulated in PCa tumours relative to normal tissue in 9 of the 10 studies." (PMID 26501081, 2015). "Patients and methods: Tumor tissue collected consecutively from 1144 NSCLC patients within a molecular screening network between March 2010 and March 2012 was analyzed for PIK3CA mutations using dideoxy-sequencing and next-generation sequencing (NGS)." (PMID 25473901, 2015). "The multiplexed SCODA mutation detection assay was used to analyze extracted DNA from patient tumor tissue and pre-operative plasma samples for the presence of mutations in KRAS, PIK3CA, BRAF and EGFR as defined in our panel." (PMID 25575824, 2015). "As multiple tumors developed in each PIK3CA/Yap mouse, the three distinct tumor types were detected in each animal investigated." (PMID 25826091, 2015). "Bram De Laere (University of Antwerp, Antwerp, Belgium) conducted research to determine the PIK3CA genotype in circulating tumor cells, at the single cell level." (PMID 28031920, 2015). "In PDA tumours harbouring wild-type KRAS, we identified BRAF and PIK3CA mutations at oncogenic hotspots expanding the spectrum of oncogenic drivers in PDA." (PMID 25855536, 2015). "When comparing protein expression with their paired-control sample, ARID1A levels were lower in 42.4% of the tumor tissues whereas c-MET and PIK3CA levels were higher in 36.4% and 63.6% of the tumor tissues analyzed." (PMID 26334097, 2015). "In summary, our results show that NGS is more sensitive than SGS for detecting PIK3CA mutations in BC samples, and that PIK3CA mutations are significantly related to HR and HER2 expression status and tumor grade." (PMID 26587011, 2015). "CDKN2A, PIK3CA, RASA1 and DMD variants were exclusively linked to smoking, chewing, HPV infection and tumor stage." (PMID 26834999, 2015). "PIK3CA mutation status was significantly associated with hormone receptor-positivity, HER2-negativity, tumor grade, and lymph node involvement." (PMID 26587011, 2015). "The largest published study evaluated the PIK3CA genotype in 687 tumor samples from patients enrolled in a prospective phase III clinical trial." (PMID 26587011, 2015).
tumor (continued). "Other clinicopathological factors such as age, gender or tumor location were statistically irrelevant to the positive expression of PIK3CA as previously reported." (PMID 26334097, 2015). "To explore the feasibility of this therapeutic strategy, we tested the safety and efficacy of inhibiting mTORC1 and AKT in PIK3CA mutant MCF7 tumor xenografts in vivo." (PMID 25961827, 2015). "PTEN M264I mutation was identified only in a TKI-refractory lesion with SCLC transformation, while PIK3CA and RB1 mutations were identified only in pre-treatment primary tumour samples." (PMID 26400668, 2015). "Tumour samples BTC27 and BTC29 were positive for mutations corresponding to PIK3CA p.H1047R or p.E542K, present at a frequency of 12.4% and 19% respectively." (PMID 26498688, 2015). "In contrast, a PIK3CA inhibitor BEZ235 dramatically inhibited tumor growth (7.5 days of the control versus unreached over 18 days, p<0.0001)." (PMID 26270481, 2015). "The c-MET and PIK3CA mRNA expression levels were independently significantly higher in tumor tissues compared with adjacent non-tumor tissues and these results were confirmed by IHC." (PMID 26334097, 2015). "The c-MET and PIK3CA expression levels were significantly higher in 32 (78.0%) and 31 (73.8%) tumor tissues compared with adjacent non-tumor tissues (P = 2.20 × 10−5 and P = 1.00 × 10−3 respectively)." (PMID 26334097, 2015). "Differences in the distribution of tumor characteristics were found between the three PIK3CA groups by Sanger/qPCR." (PMID 26452060, 2015). "Evaluable results for PTEN and PIK3CA were available for 91% (355/390) and 77% (210/274) of patients with available tumor tissue and who provided consent for tumor genetics, respectively." (PMID 25056500, 2014). "In summary, both PIK3CA exon 20 mutations and loss of PTEN expression are promising predictors of tumor suitability for anti-EGFR therapies." (PMID 24811491, 2014). "Using the Sequenom assay, we then tested for mutations in PIK3CA, AKT and PTEN genes in 140 pretreatment biopsies collected at our tumor bank." (PMID 24705275, 2014). "For example, some novel canonical mutations in PIK3CA had many mutant reads in RNA-seq but only a few mutant reads in DNA-WES, such as the example Luminal A tumor with a single DNA mutant read in the PIK3CA hotspot." (PMID 24970867, 2014). "We show that treatment with P7170 results in a marked reduction in the survival of NSCLC cells with different mutations in EGFR, KRAS, PIK3CA, or PTEN and inhibition of tumor growth in vivo." (PMID 25466244, 2014). "In the light of recent findings on the role of some molecular markers in the pathogenesis and progression of this tumor, we have also carried out molecular analyses to verify the methylation of p16 promoter and mutational status of KRAS, PIK3CA and EGFR." (PMID 25358264, 2014). "Despite genetic heterogeneity of the early neoplasias in this study (chromosome 1q and PIK3CA), a shared program of transcriptional modifications appears to characterize early neoplasias as a whole." (PMID 24887547, 2014). "The expression of PIK3CA was detected in 41 of 223 (18.4%) normal tissue samples and 250 of 406 (61.6%) tumor samples." (PMID 25054828, 2014). "DNA extracted from each tumor pair was used to determine PIK3CA and AKT1 mutation status with a sensitive and specific qPCR-based assay, and serial sections from each tumor pair were also used to assess Ki67 staining and total PTEN loss via IHC." (PMID 24520381, 2014).
tumor (continued). "The PIK3CA was significantly overexpressed in ESCC tumor specimens compared to normal samples (P<0.001)." (PMID 25054828, 2014). "We collected formalin-fixed, paraffin-embedded and fresh frozen tumor samples from AGC patients and analyzed the KRAS, NRAS, BRAF and PIK3CA mutations by direct-sequencing." (PMID 24774510, 2014). "PIK3CA genotype from the primary (notmetastatic) tumor was found to be prognostic, with patients bearing a PIK3CAmutation having a worse clinical outcome (P = 0.0001)." (PMID 25192370, 2014). "CN analysis showed that the PIK3CA locus was amplified (1.544, 1.436, and 1.316, log2) in AR+/PIK3CA mutant tumors, including one tumor (TCGA-C8-A12L) with a focal amplification of only 12 genes." (PMID 25103565, 2014). "Anti-tumor efficacy of the molecules was tested in several mouse models of human cancer including BT474 and SKOV3 (ovarian) both of which contain PIK3CA mutations (H1047R or K111N) and amplification of ERBB2 rendering the AKT pathway hyperactive." (PMID 24978597, 2014). "All 3 tumor samples had KRAS mutations, while 2 tumors contained mutations in the APC gene and the PIK3CA gene." (PMID 24943349, 2014). "Poor prognosis and significant association with Dukes' stage D suggest that tumours with KRAS and PIK3CA mutations are more likely to develop into liver metastasis." (PMID 25361007, 2014). "Among the AGC patients whose tumor tissue contained gene mutations, multiple mutations of KRAS codon 13, PIK3CA codon 545 and NRAS codon 12 were detected in only one case." (PMID 24774510, 2014). "Of the total study population, 390 patients had tissue available for biomarker analyses and 274 of these patients provided written informed consent for optional tumor genetics (that is, PIK3CA analysis)." (PMID 25056500, 2014). "There are two highly specific PI3Kα inhibitors, GDC-0032 (Genetech) and BYL719 (Novartis) that have demonstrated superior inhibition of PIK3CA mutant and amplified cell lines as well as tumor xenografts." (PMID 25428177, 2014). "In one case, a patient with PIK3CA mutations in both primary and metastatic samples showed low PTEN expression in the primary tumor and was PTEN null in the metastatic sample." (PMID 24520381, 2014). "Mutations were detected in 72 (31.9%) tumours for KRAS, in 6 (2.65%) for BRAF, in 7 (3.1%) for NRAS and in 37 (16.4%) for PIK3CA." (PMID 23374602, 2013). "There was a significant positive association between PIK3CA mutation incidence and BRCACX (17.2%) compared with BRCA2 (0%) associated tumours (P = 0.030)." (PMID 23971979, 2013). "Given the high number of PIK3CA mutations in human cancer, this finding could have a significant impact on the design of metformin-based therapies that aim to influence both the early stages of tumor formation and progression and cancer recurrence in advanced tumors." (PMID 23986086, 2013). "At the tumour level, somatic mutations in EGFR, KRAS, BRAF, PTEN and PIK3CA are associated with poor response to anti-EGFR therapy in CRC." (PMID 24152305, 2013). "We found an association between PIK3CA mutation and poor overall survival for patients with a BRAF wild-type tumor." (PMID 23785428, 2013). "Histological examination of a representative rapamycin-resistant FC PIK3ca* tumor demonstrated a similar morphology to cancers from controls." (PMID 23593290, 2013). "Tumour DNA was pyrosequenced for KRASc.146, BRAF, NRAS, and PIK3CA mutations, and predefined molecular subgroups were analysed for interaction with the effect of panitumumab." (PMID 23725851, 2013). "PTEN analysis using the validated IHC assay, along with testing for MSI, PIK3CA, and BRAF mutations, are among the correlative studies that will be performed on tumor specimens from patients treated in this study." (PMID 24156022, 2013).
tumor (continued). "Combinations of drugs that target both pathways were found to be more effective than single drugs in reducing tumour volume and in downregulating the expression of phosphoAKT and PIK3Ca." (PMID 23441137, 2013). "PIK3CA-mutated tumors were associated with loss of MGMT expression (35% vs. 20%; P = 0.001) and the presence of tumor mucinous differentiation (54% vs. 32%; P<0.001)." (PMID 23785428, 2013). "Tumor tissues were tested for HER2-status and mutations in the PTEN, PIK3CA, AKT1, CTNNB1, and E-cadherin type 1 genes." (PMID 23930209, 2013). "PTEN underexpression was significantly mutually exclusive with PIK3CA, PIK3R1 and AKT1 mutations (p = 0.00016), as it was observed in only one AKT1 mutated tumor and 14 PIK3CA mutated tumors." (PMID 24229379, 2013). "Of the six patients assessed for bone metastasis PIK3CA status in this study, primary tumor material was available for four." (PMID 22970388, 2012). "All 4 hotspots in PIK3CA, E545K, E542K, H1047R, H1047L, are known to be oncogenic in various tumor types." (PMID 22870241, 2012). "Immunohistochemical staining of tumor specimens for p110α is therefore likely going to underestimate the impact of p110α and changes in PIK3CA status." (PMID 22355357, 2012). "In summary, we established 5 PDECX mouse models and demonstrated tumor regression in response to Trastuzumab treatment in a HER-2 IHC 2+ model, but resistance in a HER-2 IHC 2+/PIK3CA mutated model." (PMID 22935382, 2012). "Recognized tumor genes, such as EVI1 and MDS1, and genes associated previously with CC (TERC, TNFSF10, and PIK3CA) are located in this region." (PMID 22412903, 2012). "This study demonstrates Trastuzumab-induced tumor regressions in HER-2 positive tumors, and highlights PIK3CA mutation as a potential resistance mechanism to Trastuzumab treatment in pre-clinical patient-derived EC xenograft models." (PMID 22935382, 2012). "PIK3CA, HRAS and AKT1 (all n = 1) mutations were detected in FFPE tumor specimens, while NRAS, PIK3CA and AKT1 (all n = 1) mutations were found in cpDNA samples." (PMID 23144797, 2012). "Understanding the metabolic dependencies of PIK3CA mutant cancers will provide critical information for the design of effective therapies and tumour visualisation strategies." (PMID 23028762, 2012). "Both KRAS and PIK3CA mutations were evaluated for association with several pathological parameters: sex, age at diagnosis, anatomical location of primary CRC, tumour grading, AJCC stage of the disease." (PMID 22931052, 2012). "We retrospectively analyzed objective tumor response rate, (ORR) progression-free (PFS) and overall survival (OS) with respect to the mutational status of KRAS, BRAF, PIK3CA and PTEN expression in mCRC patients treated with a cetuximab-based regimen." (PMID 22569004, 2012). "Among available DNA samples, 384 primary tumours were also evaluated for occurrence of BRAF (in exon 15) and PIK3CA (in exons 9 and 20) mutations." (PMID 22931052, 2012). "Primary tumor samples were available for four of the six patients assessed for PIK3CA status in their bone metastases." (PMID 22970388, 2012). "KRAS and BRAF mutations were mutually exclusive, whereas, three tumours carried both KRAS and PIK3CA mutations." (PMID 21283802, 2011). "In this pathway, PIK3CA, KRAS and BRAF genes are frequently activated by mutations in various tumour types, including CRC with frequencies of 10–30%, 30–40% and 5–22%, respectively." (PMID 21673680, 2011). "Previous studies have reported that MSI, CIMP, BRAF mutation, PIK3CA mutation, and LINE-1 tumor hypomethylation were associated with CRC prognosis, and that lymphocytic infiltration is associated with many of these molecular variables." (PMID 24212797, 2011).
tumor (continued). "TTP and OS to the ≥2nd line cetuximab-containing treatment according to KRAS, BRAF, PIK3CA mutations status, PTEN protein expression, AREG and EREG mRNA expression and grade of skin rash in the KRAS WT patients′ population." (PMID 21283802, 2011). "Furthermore, the gene encoding for the p110α subunit, PIK3CA, is amplified, overexpressed and frequently mutated in many cancers; critically, these mutations have been shown to reduce cellular dependence on growth factors, to attenuate apoptosis, and to facilitate tumour invasiveness." (PMID 21649578, 2011). "In conclusion, we studied the prevalence of PIK3CA, RAS (KRAS, NRAS), and BRAF mutations in diverse tumor samples and identified a high frequency of coexisting PIK3CA and BRAF or RAS mutations." (PMID 21829508, 2011). "More recently, the analysis of KRAS, BRAF and PIK3CA in tumour invasion fronts, lymph nodes and distant metastases revealed a discordance between primary tumours and lymph node metastases of 31, 4 and 13%, respectively." (PMID 21139621, 2010). "Of note, pik3ca gene abnormalities appear to occur at relatively late stages of neoplasia, near the time where tumors begin to invade and metastasize." (PMID 21203412, 2010). "The frequency of mutations for KRAS, PIK3CA, and BRAF were tested for correlation to the degree of differentiation and to the prevalence of mucin in the tumor." (PMID 20233444, 2010). "This can be achieved by either targeting both BRAF and CRAF or BRAF and PIK3CA simultaneously in NRAS mutant tumor cells." (PMID 19492075, 2009). "This is in contrast to studies in other tumor types where the PIK3CA pathway is shown to be sufficient for tumor initiation and maintenance." (PMID 19492075, 2009). "Patients with HER2-positive tumours having PIK3CA amino acid changes derived benefit from lapatinib." (PMID 19844234, 2009). "The identification of PIK3CA validated our approach to identify kinases that are essential for tumour cell survival." (PMID 19357772, 2009). "PIK3CA gene (exon 9; 14–20) mutation analysis was conducted in EGF100642; 30 tumour samples had sufficient quantities for of genomic DNA." (PMID 19844234, 2009). "We retrospectively analyzed objective tumor response, progression-free (PFS) and overall survival (OS) together with the mutational status of KRAS, BRAF, PIK3CA and expression of PTEN in 132 tumors from cetuximab or panitumumab treated mCRC patients." (PMID 19806185, 2009). "We also tested these lines in vivo to see if targeting both BRAF and PIK3CA or both MEK1+2 and PIK3CA will lead to delayed tumor growth." (PMID 19492075, 2009). "Our data suggest that the inflammatory microenvironment can edit back the tumor cells through activation of the NF-κB/PIK3CA pathway, with multifaceted results that promote survival." (PMID 18335034, 2008). "In contrast to KRAS and PIK3CA mutations, BRAF mutations are associated with tumours harbouring CpG Island methylation phenotype (CIMP), MLH1 methylation and microsatellite instability (MSI)." (PMID 18782444, 2008). "Further, whenever PIK3CA mutations occur in CRC they can occur in concomitance with activating KRAS-BRAF mutations, both in MSI and MSS tumours." (PMID 18782444, 2008). "HIF binding sites were identified in the PIK3CA promoter region and strong nuclear HIF staining was detected in the areas where tumor cells upregulate PIK3CA in vivo." (PMID 18335034, 2008). "Here, we report a novel mechanism through which the tumor microenvironment activates the PIK3CA oncogene." (PMID 18335034, 2008). "Based on these findings and previously reported evidence, we propose a novel model to interpret the function of PIK3CA in solid tumors and its regulation by the tumor microenvironment." (PMID 18335034, 2008).